S100A8 (S100 calcium binding protein A8)
Diseases named in the same sentence as S100A8 in open-access papers (continued):
Sharing a sentence is not in itself a finding about the gene and the disease.
asthma (continued). "Indeed, we recently confirmed its ability to scavenge hypohalous acid oxidants in human asthma, and S-nitrosylated S100A8 inhibits leukocyte transmigration triggered by mast cell degranulation in the microcirculation." (PMID 25098409, 2014). "S100A8 and A9, also known as calgranulins, have been shown to play a role in the initiation and regulation of chronic and acute inflammatory diseases, including asthma." (PMID 20691077, 2010). "In keeping with this, we found that S100A8 scavenges oxidants, particularly peroxide, and hypochlorite (HOCl/OCl−) generated by the myeloperoxidase system and may modulate redox in chronic inflammatory lesions such as in human atheroma and human asthma." (PMID 25098409, 2014). "S100A8, S100A9, S100A12, and RETN are universally upregulated in various cell types of asthma patients." (PMID 41550933, 2025). "S100A8 and S100A9 can promote mucus hypersecretion typical of asthma in BECs, which is consistent with our previously published works documenting reduced MUC5AC post-BT along with IL-13+ cells in bronchial biopsies collected from a similar cohort." (PMID 37996952, 2023). "We first documented baseline expression of S100A7, S100A8 and S100A9 genes in severe asthma and compared to BECs obtained from healthy controls." (PMID 37996952, 2023). "IPA analyses of increased abundance of the four proteins (MMP9, AGT, S100A8, CTSC) in the POLD group (when compared to PTc) suggested increased neutrophil accumulation, which is a reasonable hypothesis given the association of neutrophilic inflammation with wheezing in asthma." (PMID 37474963, 2023). "In asthma, the SERPINB3 / B4 complex increases S100A8 production and inflammation by activating P38 / MAPK." (PMID 37422662, 2023). "We believe that the inflammatory response due to S100A8 and S100A9 is a critical factor in asthma pathogenesis." (PMID 32174780, 2020). "In the lung, increased levels of S100A8, S100A9 and S100A12 have been found in asthma, cystic fibrosis, chronic obstructive pulmonary disease, idiopathic pulmonary fibrosis, acute respiratory distress syndrome and ventilator associated lung injury." (PMID 25706559, 2015). "In the current study, a similar regulation of the expression of two S100 proteins, S100A8 (also known as calgranulin A, MRP8) and S100A11 (also known as calgizzarin, S100C), was observed in acupuncture-treated OVA-induced asthma onset rats." (PMID 23304218, 2012). "Therefore, future studies investigating S100A8/A9 and TLR4 neutralization will be required to determine its potential role in experimental severe asthma." (PMID 36776857, 2023). "Although levels of RAGE ligands S100B, S100A8/A9, S100A1, S100A6, AGEs may have a biomarker role in cardiovascular disease, in asthma, there are scarce data advocating such a role." (PMID 37371535, 2023). "In contrast, CRAMP, S100A8, and S100A9 were significantly decreased in the lung tissues of allergen HDM-challenged mice, a model of airway inflammation that is used for preclinical studies of asthma." (PMID 32973796, 2020). "Sputum from subjects with asthma (n = 87) or COPD (n = 73) and ACO (n = 68) or from smokers (n = 62) and never-smokers (n = 62) was analyzed for high mobility group protein B1 (HMGB1), heat shock protein 70 (HSP70), LL-37, S100A8, and galectin-3 (Gal-3)." (PMID 31848359, 2019). "Acupuncture could inhibit the S100 protein/RAGE-mediated inflammatory signaling pathway by downregulating the proteins S100A8, S100A9, and RAGE while upregulating sRAGE expression, which would to reverse the inflammatory process of asthma." (PMID 23304218, 2012). "Our results indicate that acupuncture downregulates the expression of proinflammatory proteins (e.g., S100A8, RAGE, and S100A11) and upregulates the expression of anti-inflammatory proteins (e.g., CC10, ANXA5, and sRAGE) in the lung tissues of rats with asthma onset." (PMID 23304218, 2012).
asthma (continued). "Moreover, the inhibition of S100A8 and S100A9 reduced the migration of inflammatory cells into the lungs in a mouse model of asthma." (PMID 23304218, 2012). "In our studies, the increased expression levels of S100A8, S100A9, and S100A11 in asthma onset in rats were downregulated after acupuncture, which suggests that acupuncture had an effect on the regulation of inflammatory reactions in asthma." (PMID 23304218, 2012). "Aligned to that, elevated S100A8/A9 levels are observed in the serum and sputum of asthmatic patients, particularly during episodes of exercise-induced bronchoconstriction, without any difference between the subgroups of asthma or compared to COPD." (PMID 41164170, 2025). "During peak exercise, the strong correlation between S100A8/A9 and MBP in half-marathoners (r = 0.90, p = 0.006) points to synchronized neutrophilic and eosinophilic activation under acute stress—reminiscent of the mixed inflammation phenotype observed in certain asthma subtypes." (PMID 40723384, 2025). "Epithelial expression of S100A7 and S100A8 pre-BT negatively correlated with ACCS score (r = − 0.6; p-value = 0.03 and r = − 0.7; p-value = 0.006 respectively) suggesting that higher expression of these proteins might indicate a poorer asthma control." (PMID 37996952, 2023). "Acupuncture can systematically regulate this inflammatory signaling pathway at different levels through the regulation of several key nodal proteins, including CC10, S100A8, S100A9, RAGE, sRAGE, and RhoGDI2, which may explain, at least in part, the anti-inflammatory effect of acupuncture in asthma." (PMID 23304218, 2012). "Moreover, the inhibition of S100A8 and S100A9 could reduce the migration of inflammatory cells into the lungs in a mouse model of asthma." (PMID 20691077, 2010).
colon carcinoma (40 papers, 2008 to 2024). "As a hallmark of inflammatory conditions, myeloid-derived S100A8/A9 interacted with RAGE on colon tumor cells and activated NFκB signaling pathways to promote tumor growth and metastasis in mouse models." (PMID 39337548, 2024). "S100A8/A9 has been implicated in tumor promotion including colon cancer cell proliferation, where it also provides a plausible mechanism for colitis-associated colon cancer initiation and progression." (PMID 27379212, 2016). "Therefore, S100A8/A9 in EVs are implicated in the formation of premetastatic niches in distal metastatic organs and tumor cell migration in colon cancer." (PMID 35936690, 2022). "Key genes associated with colon tumor progression are reportedly activated by S100A8/A9." (PMID 22509329, 2012). "S100A8 facilitates colon cancer cell proliferation, invasion, and metastasis through the CXCL5/CXCR2 biological axis." (PMID 38817853, 2024). "Overexpression of S100A8/S100A9 in mouse colon cancer cells CT26.WT led to differential increases in the secretion levels of various cytokines (CXCL5, CXCL11, GM-CSF, G-CSF, IL1a, IL1b, sTNF RI, and CCL3)." (PMID 38817853, 2024). "In conclusion, our findings offer compelling evidence that S100A8 amplifies the proliferative and invasive properties of colon cancer cells by activating the CXCL5/CXCR2 pathway." (PMID 38817853, 2024). "We discovered that the expression of S100A8 in colon cancer cells led to increased levels of CXCL5 and its corresponding receptor, CXCR2." (PMID 38817853, 2024). "Transfection of S100A8 or S100A9 expression vectors into colon cancer cells significantly activated NF-κB, STAT3, and ERK-MAPK, highlighting the role of S100A8/A9 as potent cancer promoters by orchestrating key connections within the signaling cascade." (PMID 38817853, 2024). "We observed that S100A8-transfected colon cancer cells formed significantly more lung metastases than did cells transfected with the empty vector (P<0.01)." (PMID 38817853, 2024). "Carboxylated glycans are expressed on a RAGE subpopulation on colon tumor cells and facilitate S100A8/A9 binding to RAGE results in NF-κB activation and cancer cell proliferation." (PMID 33117687, 2020). "Myeloid progenitors infiltrate into dysplasia sites in human adenoma and colon tumor tissue and secrete S100A8 and S100A9." (PMID 33117687, 2020). "In the functional study of core down‐regulation factors, it was found that IL6, GM‐CSF, IL11, CCL3 and S100A8/9 increased the viability of colon cancer cell lines and decreased the apoptosis rate of colon cancer cells with irradiation and chemical treatment." (PMID 31650683, 2020). "In the functional study of core down‐regulation factors, it was found that IL6, GM‐CSF, IL11, CCL3 and S100A8/9 increased the viability and decreased the apoptosis rate of colon cancer cells with irradiation and chemical treatment." (PMID 31650683, 2020). "Previous studies revealed that exogenous S100a8/a9 protein increases the proliferation of colon cancer cells in vitro." (PMID 29326691, 2017). "Recently, the inflammatory factor S100A8 was found to activate the Akt1-Smad5-Id3 axis, which promoted the proliferation, invasion and metastasis of colon cancer cells." (PMID 27177089, 2016). "Studies using bone marrow chimeric mice revealed that S100A8/ A9 expression on myeloid cells is essential for the development of colon tumors." (PMID 23166536, 2012). "Inhibitor experiments confirmed our hypothesis, validating that S100A8 enhances the proliferation of colon cancer cells and boosts their invasive metastatic potential through the CXCL5/CXCR2 bioaxis pathway." (PMID 38817853, 2024). "Moreover, Transwell invasion assays showed that S100A8 transfection substantially increased the invasiveness of colon cancer cells, facilitating their penetration through the matrix gel and migration to the lower compartment." (PMID 38817853, 2024).
colon carcinoma (continued). "Moreover, S100A8 enhances the proliferation and invasion of colon cancer cells, mediated by the chemokine CXCL5 and its receptor CXCR2." (PMID 38817853, 2024). "Although it has been reported that the S100A8/S100A9 heterodimer complex promotes colon tumor progression via the RAGE-dependent pathway, S100A8-mediated TLR4 activation in host cells could play a role in inflammatory cytokine/chemokine production." (PMID 35780158, 2022). "Other reports have indicated that S100 protein can increase Wnt signaling; for example, the role of S100A8 is partially dependent on the activation of Wnt/β-catenin signaling, and inhibition of S100A4 expression impedes colon cancer progression caused by the Wnt/β-catenin signaling pathway." (PMID 35279748, 2022). "Studies have shown that S100A8/A9 expression on myeloid cells is necessary for colon tumor growth." (PMID 33117687, 2020). "In breast and colon cancer cells, S100A8/A9 is found to induce phosphorylation of ERK and JNK." (PMID 25811984, 2015). "Recently, ZC3H12A has been identified as one of the upregulated genes in S100A8/A9-activated colon tumor cells, whose products promote leukocyte recruitment, angiogenesis, tumor migration, wound healing, and formation of premetastatic niches in distal metastatic organs." (PMID 23658834, 2013). "Moreover, S100A8 promotes the proliferation and invasion of colon cancer cells." (PMID 38817853, 2024). "Notably, S100A8 significantly promotes colon cancer cell proliferation and invasive metastasis." (PMID 38817853, 2024). "Our analysis revealed significant upregulation of S100A8 and S100A9 in colon cancer tissues compared to normal intestinal mucosa in the GSE9438 dataset." (PMID 38817853, 2024). "Utilizing Western blotting, we examined three colon cancer cell lines (CT26, SW620, and SW480) that were genetically modified to overexpress S100A8 and S100A9." (PMID 38817853, 2024). "The aim of this study was to elucidate the effects and potential mechanisms of high S100A8 and S100A9 expression in colon cancer cells on the secretion of inflammatory factors and malignant transformation of tumors." (PMID 38817853, 2024). "The binding of S100A8/S100A9 on RAGE and carboxylated glycan in colon cancer activates the NF-κB pathways, resulting in a life-threatening link between inflammation and cancer." (PMID 36613714, 2022). "We identified that BGN, S100A8, S100A9, and TNC expression levels were elevated significantly in colon cancer samples." (PMID 32050430, 2020). "S100A8 and S100A9 proteins are also regarded as signals to recruit PMN and PMN-MDSC to pre-metastatic sites in colon cancer." (PMID 32153594, 2020). "Furthermore, S100a8 and S100a9 promoted colorectal tumorigenesis by recruiting macrophages, and promoting the proliferation and invasion of colon cancer cells, suggesting that the aberrant expression of S100a8 or S100a9 is linked to non-resolving inflammation and ultimately to carcinogenesis." (PMID 29326691, 2017). "To investigate the impact of elevated S100A8 and S100A9 expression on the secretion of inflammatory factors by colon cancer cells, we transfected CT26 colon cancer cells with overexpression plasmids containing S100A8 and mS100A9, both individually and in combination." (PMID 38817853, 2024). "RAGE has been proposed to serve as a primary receptor for S100 proteins in the extracellular space, and plays an important role in S100A8- or S100A9-induced proliferation and migration of prostate and breast and colon cancer cells involving the MAPK/NF-κB signaling." (PMID 23637971, 2013). "In addition, S100A8 and S100A9-activated colon cancer cells showed an upregulation of LCN2 gene expression compared to non-stimulated cells." (PMID 22559235, 2012). "In another study, LCN2 gene expression was upregulated in S100A8 and S100A9-stimulated colon cancer cells compared to non-stimulated cells." (PMID 34072157, 2021).
autoimmune disease (39 papers, 2012 to 2025). A disorder resulting from loss of function or tissue destruction of an organ or multiple organs, arising from humoral or cellular immune responses of the individual to their own tissue constituents. "This suggests a strong association between the presence of autoimmune disease markers S100A8 and S100A9 and the development of spontaneous ankylosing spondylitis in crab-eating monkeys." (PMID 39877611, 2025). "S100a8/a9 is necessary to induce autoreactive CD8+ T lymphocytes in autoimmune diseases, which causes inflammation mediated by TLR4 signaling and results in elevated interleukin-17 (IL-17)." (PMID 37396347, 2023). "S100a8 and s100a9 are in the focus of rigorous research due to their association with numerous diseases, including acute and chronic inflammatory diseases, autoimmune diseases, cancer, and neurodegenerative diseases." (PMID 28769105, 2017). "Dysregulated S100A8/S100A9 expression has been linked to various inflammatory and autoimmune diseases." (PMID 41476978, 2025). "Encouraging results have been obtained in experimental and clinical interventional studies with S100A8/A9 blockers as a form of therapeutic management for autoimmune disease and cancer." (PMID 41155408, 2025). "Encouraging results have been obtained in experimental and clinical interventional studies with S100A8/A9 blockers on autoimmune disease and cancer." (PMID 41155408, 2025). "Abnormal expression and aberrant function of S100A8/S100A9 are closely associated with the onset and progression of a wide range of diseases, including inflammatory diseases, tumors, and autoimmune diseases." (PMID 41476978, 2025). "Several previous studies performed that S100A8/S100A9 can show a pro-inflammatory activity in some autoimmune diseases and these genes were reportedly upregulated in inflammatory states." (PMID 40540498, 2025). "In IBD, particularly in autoimmune diseases like CD, S100A8 is present in high concentrations and is released to stimulate cytokine secretion." (PMID 40630894, 2025). "The CD52+ Mo-Mp subtype expressed CD52, S100A9 and S100A8, which has been reported as a bi-directional regulator in inflammation of autoimmune diseases via T cell activation and Treg induction." (PMID 38601143, 2024). "S100A8/A9 are granulocyte and monocyte specific and play a prominent role in a variety of pathological processes, such as inflammation, infection, and autoimmune diseases." (PMID 38982370, 2024). "Serum levels of S100A12 and S100A8/A9 were shown to be increased in various inflammatory and autoimmune diseases, and complement activation was reported to occur at sites expressing S100A8/A9." (PMID 37146011, 2023). "S100A8 and S100A9, both secreted factors associated with the ECM, have been associated with acute and chronic inflammatory conditions and autoimmune diseases." (PMID 36672527, 2022). "A study has found that S100A8 expression levels increased in neurodegenerative disorders and inflammatory and autoimmune diseases." (PMID 36671424, 2022). "The serum level of S100A8/A9 complex is significantly elevated during wound healing process, tumorigenesis, and autoimmune diseases and is used as an extremely sensitive biomarker for the early stage of local inflammatory activity." (PMID 35592707, 2022). "It is believed that S100A8 is closely involved in inflammation, and it has previously been identified as a proinflammatory factor in arthritis and autoimmune disease." (PMID 33393624, 2021). "Using small-molecule inhibitors that block off S100A8/A9 activity can exhibit beneficial functions on disease relative activities in animal models of autoimmune diseases such as RA." (PMID 33397492, 2021). "Toll-like receptor 4 (TLR4) and one of its endogenous ligands myeloid-related protein 8 (MRP8 or S100A8), especially expressed in macrophages, play an important role in diabetic nephropathy and autoimmune disorders." (PMID 32080297, 2020).